SERTAD1 (SERTA domain containing 1)
Diseases named in the same sentence as SERTAD1 in open-access papers (continued):
Sharing a sentence is not in itself a finding about the gene and the disease.
cancer (continued). "To investigate the clinicopathological function of SERTAD1 mRNA levels in cancer patients, we collected studies for meta-analysis from PrognoScan database." (PMID 30857225, 2019). "The effect of SERTAD1 alteration in cancer patient’s survival and their outcome has been also studied." (PMID 30857225, 2019). "Previous studies had shown that Sertad1 was highly expressed in carcinomas from pancreas, that considered Sertad1 as an oncoprotein." (PMID 29179704, 2017). "Overexpression of SERTAD1 induces genomic instability in cancer cell lines and inhibits oxidant-induced cell death." (PMID 24498427, 2014). "Our results also showed that co-inhibition of SERTAD1 and autophagy magnified apoptosis, indicating the concomitant targeting of SERTAD1 and other PCDs may help to improve cancer-killing strategies and overcome anoikis resistance." (PMID 35625886, 2022). "SERTAD1 expressed in cancer tissue and control patient survival outcome." (PMID 30857225, 2019). "SERTAD1 targeted therapies might be proved effective and a novel approach to control various types of cancers." (PMID 30857225, 2019). "In this line, we aimed to investigate whether the alteration in the SERTAD1 signature affects cancer relapse free and overall survival in different cohort studies." (PMID 30857225, 2019). "SERTAD1 elevated mRNA levels significantly effects the overall patient survival in cancers." (PMID 30857225, 2019). "Given this overall information, we propose a novel pathway in which SFN could defer cancer cell growth in the G1 phase through downregulation of SERTAD1 proteins followed by dissociation of the CCND–CDK4 complex." (PMID 31084542, 2019). "Apart from inducing down-regulation of genes, the GSC exosomes also induced up-regulation of cancer-related genes such as SERTAD1 and SEC61G which would support the hypothesis that exosomes released by tumor cells can promote tumorigenesis." (PMID 29163818, 2017). "Therefore, we investigated SERTAD1 percentage alteration frequency with different types of cancers." (PMID 30857225, 2019). "Therefore, aberration in SERTAD1 expression play a key role in the cancer patients’ survival." (PMID 30857225, 2019). "To elucidate the mechanism of cancer-specific mitophagy, we initially focused on TRIP-Br1 (also known as SERTAD1/SEI-1/SEI1/p34SEI-1) protein." (PMID 35813469, 2022). "This meta-analysis demonstrates a robust evidence of an association between higher or lower SERTAD1, alteration and without alteration of SERTAD1 in cancers in terms of survival and cancer invasiveness." (PMID 30857225, 2019). "The role of SERTAD1 in anti-cancer drug resistance is not known." (PMID 35625886, 2022). "In an effort to identify the proteins responsible for the resistance of cancer cells to nutrient starvation-derived cell death, we initially focused on the TRIP-Br1 (transcriptional regulator interacting with the PHD-bromodomain 1, also known as SERTAD1/SEI-1/p34SEI-1) oncoprotein." (PMID 26334958, 2015).
tumor (10 papers, 2010 to 2025). "Because SERTAD1 expression is increased in hypoxic conditions, it would be interesting to examine the role of SERTAD1 in the formation and shedding process of CTCs from the primary tumor." (PMID 35625886, 2022). "An enhanced level of SERTAD1 remarkably induced tumor induction, ubiquitination and genomic instabilities." (PMID 30857225, 2019). "However, distinct link between SERTAD1, tumor initiation and its pathogenesis is still remained to explain extensively." (PMID 30857225, 2019). "Recently, SERTAD1 have been demonstrated to be localized in tandem within a 19q13 amplicon frequently found in diverse human tumors, consistent with their putative role as oncogenes that promote tumor development." (PMID 30857225, 2019). "As our current findings, an elevated expression of SERTAD1 induces tumor development." (PMID 30857225, 2019). "SERTAD1 was found significantly elevated levels in most of tumor samples." (PMID 30857225, 2019). "According to the expression levels and regression coefficients, the downregulated BAX, PWP2, SERTAD1, S1PR4, ZFAND1, NUDT13 and ZNF107 with HR < 1 were considered as tumor suppressors, whereas the MVD, BAD, CPNE7, CPNE7, UTP23 and ZNF124 upregulated with HR > 1 were regarded as oncogenes." (PMID 36685828, 2022).
infection (1 paper, 2020). The state of being infected such as from the introduction of a foreign agent such as serum, vaccine, antigenic substance or organism. "Interestingly, most animals infected with CSFV E2ΔSERTAD1v survived infection, indicating that the amino acid residues of E2 identified to bind host SERTAD1 protein may play an important role in CSFV virulence in swine." (PMID 32283651, 2020).
SERTAD1 also shares sentences with these, for which no sentence is quoted: metabolic disease (2 papers); bladder carcinoma (1); colon cancer (1); diabetes (1); fibrosarcoma (1); Glucose intolerance (1); head and neck squamous cell carcinoma (1); invasive breast carcinoma (1); lymphoma (1); nasopharyngeal carcinoma (1); pancreatic ductal carcinoma (1); papilloma (1); peritonitis (1); squamous cell lung carcinoma (1); stomach adenocarcinoma (1); teratoma (1); viral infection (1).